RNU7-70P (RNA, U7 small nuclear 70 pseudogene)
Synonyms: U7.70
Gene: Small nuclear RNA gene on chromosome 1 (112,634,719 to 112,634,784, reverse strand). Ensembl gene ENSG00000252750.
Homologues: Orthologues: chimpanzee U7 (94% identical), macaque U7 (80% identical). Paralogues in human: RNU7-37P (82% identical), RNU7-73P (82% identical), RNU7-88P (82% identical), RNU7-94P (82% identical), U7 (82% identical), RNU7-19P (80% identical), RNU7-20P (80% identical), RNU7-40P (80% identical), RNU7-48P (80% identical), RNU7-50P (80% identical), RNU7-62P (80% identical), RNU7-12P (79% identical), and 142 more.